MMP1 (matrix metallopeptidase 1)
Diseases named in the same sentence as MMP1 in open-access papers (continued):
Sharing a sentence is not in itself a finding about the gene and the disease.
tumor (continued). "We identified CD36, MMP1, TGFBR3, TWIST2, ITGB1, and FGF19 as associated with poorer outcomes: CD36 enhances tumour stemness and growth, MMP1 facilitates metastasis, TGFBR3 and TWIST2 promote EMT and invasion, ITGB1 supports cell adhesion and survival, and FGF19 drives proliferation." (PMID 41007296, 2025). "This study is the first to elucidate the crucial role of MMP1 in SG resistance in BC, demonstrating that the upregulation of MMP1 is closely associated with SG resistance and affects tumor cell migration and invasion through the activation of the NF-κB signaling pathway." (PMID 40287412, 2025). "We found that MMP1 expression was significantly higher in RCC tissues than in normal kidney tissues and that higher MMP1 expression was associated with a higher tumor stage (P = 0.0473) and tumor grade (P = 0.0008) and poorer overall 10-year survival (P = 0.017)." (PMID 40386045, 2025). "Our data demonstrated a significant association between MMP-1 mRNA level and clinicopathological parameters, including tumour size (p < 0.0153), cellular differentiation (p < 0.0225), tumour stage (p < 0.0016), lymph node metastasis (p < 0.0285), and distant metastasis (p < 0.0128)." (PMID 35456495, 2022). "Additionally, a significant association between the upregulation of MMP-1 and tumour location was noted." (PMID 35456495, 2022). "The poor survival associated with high MMP1 expression + high macrophage/MDSC/T cell CD4 + infiltration also indicated that these risk factors might contribute to tumor progression synergistically." (PMID 35948625, 2022). "Combined with the phenomenon that MMP1 expression was closely associated with CAFs infiltration, we concluded that MMP1 not only acted to degrade extracellular matrix and promote tumor metastasis, but also promoted the production of extratumoral matrix by CAFs, thereby promoting tumor development." (PMID 36727076, 2022). "Numerous studies have suggested that MMP1 is associated with tumor invasion and metastasis." (PMID 35444950, 2022). "In addition, we calculated spearman’s correlation between MMP1 expression and tumor mutational burden and microsatellite instability in each cancer type." (PMID 36727076, 2022). "The results suggested that MMP1 was associated with tumor immunity." (PMID 36727076, 2022). "Overexpression of MMP1 levels was significantly associated with tumor size >5cm, grade III, presence of perineural invasion, and a worse T stage and was shown to be a good predictor for all of these clinicopathological variables according to the high AUC values." (PMID 35806108, 2022). "Additionally, we observed that upregulation of MMP-1 was associated with tumour size, cellular differentiation, lymph nodes metastasis, distant metastasis, and poor survival." (PMID 35456495, 2022). "However, high MMP1 expression was positively associated with advanced tumor size, advanced pathological grade, and cervical node metastasis and with P-value 0.0097, 0.0006, and 0.0280, respectively." (PMID 36105241, 2022). "To date, it is known that the increased expression of the MMP1 protein in tumor tissue is associated with metastatic lesions of lymph nodes in BC, and a decrease in MMP1 gene expression reduces the metastatic potential of BC cells both in vitro and in vivo in animal experiments." (PMID 34149804, 2021). "MMP1, also known as matrix metalloproteinase-1, encodes a protein of 469 amino acid residues and is a kind of photolytic enzyme closely related to tumor genesis, invasion and metastasis." (PMID 34721544, 2021). "Mmp1 is from a family of genes strongly linked to cell motility, and is necessary for basement membrane degradation and invasive behaviours by Ras85DV12/scrib–/– tumours." (PMID 32117973, 2020). "Moreover, tumor cells from this stage IV sample show upregulation of genes related to EMT, angiogenesis, and metabolic pathways, including those that have been previously associated with tumor progression such as MMP1, S100A2, TSPAN8, and IGFBP2." (PMID 33170151, 2020).
tumor (continued). "Expression of MMP-1 is associated with a tumor invasion and development of metastases." (PMID 31582998, 2019). "Combined with previous reports that MMP-1 expression is associated with poor prognosis in esophageal cancer, the study suggested that chemerin could elicit pro-tumor effects in ESCC." (PMID 30555465, 2018). "In addition, MMP1 was the only gene associated with tumor aggressiveness to play a role in at least five of the cancer-related biological processes." (PMID 30416686, 2018). "Furthermore, MMP1 expression has been strongly associated with tumor metastasis and adverse outcomes in mCRC and has been suggested as a potential prognostic and therapeutic target." (PMID 29342159, 2018). "The levels of MMP1 expression are associated with poor prognosis, suggesting that MMP1 may contribute to multiple processes during tumor growth and progression." (PMID 27995036, 2016). "MMP1 is produced by tumor cells as well as by tumor associated stroma." (PMID 24972610, 2014). "However, we don’t know exactly, if an observed association between CTC_EMT and MMP1 in tumor stroma, was due to expression of MMP1 in stromal fibroblasts, or stromal like cancer cells that underwent EMT." (PMID 24972610, 2014). "It has been suggested that oxidative stress is induced in TP-overexpressing cells, which leads to the upregulation of vascular endothelial growth factor (VEGF), matrix metalloproteinase (MMP)-1, and IL-8, which are implicated in angiogenesis and tumour cell invasion." (PMID 25350954, 2014). "In addition, several studies have reported that MMP1 is produced by invasive tumor cells in vivo as well as in vitro and is thus associated with vascular remodeling, angiogenesis and tumor progression." (PMID 24883044, 2014). "Moreover, high levels of both phosphorylated p65 (serine 536) and MMP1 in neoplastic cells were positively associated with advanced tumor stages, as well as with regional lymph node metastasis in OSCC." (PMID 24063540, 2013). "Using a dicotomised HER2 grouping into immunonegative (0 - 1+ classes) and immunopositive (2+ - 3+ classes) groups, we also found a significant positive association between HER2 and MMP-1 expression in tumour cells (p = 0.0086) and in stromal cells (p = 0.0038)." (PMID 21835023, 2011). "IL1RN, MAL and MMP1 are prospective tumor diagnostic markers for HNSCC." (PMID 19835631, 2009). "Similarly, the presence of the MMP1 gene, responsible for encoding matrix metalloproteinase 1, suggests that inhibiting tumour invasion and metastasis could be critical in improving patient outcomes." (PMID 39120548, 2024). "We recently demonstrated that eye imaginal disc tumours, caused by the expression of constitutively activate Ras (RasV12) and an RNAi against the polarity protein disc‐large 1 (dlg1RNAi), secrete two cachectic factors: ImpL2 and Matrix metalloproteinase 1 (Mmp1)." (PMID 38014610, 2023). "Moreover, high MMP1 expression was associated with advanced clinical stages in 8 tumor types." (PMID 36727076, 2022). "In addition, MMP1 expression was closely related to cancer-associated fibroblast (CAFs) infiltration in a variety of cancers and played an important role on immune infiltration score, tumor mutational burden (TMB) and microsatellite instability (MSI)." (PMID 36727076, 2022). "Furthermore, as Egr-dependent expression of Matrix metalloprotease-1 (Mmp1) has been linked with invasiveness in rasV12/scrib tumours, we assessed whether this target would also require egr/grnd-mediated JNK activation in ph tumours." (PMID 29357360, 2018). "Expression of MMP-1 in proliferating (Ki-67+) cells of intestinal metaplasia and in Barrett-associated adenocarcinomas may thus sustain multi-step carcinogenesis and further tumor growth." (PMID 20946664, 2010).
tumor (continued). "In addition to salivary detection, MMP1 could be tested at the RNA level for its ability to identify small tumor clusters in diagnostic biopsies, surgical margins or lymph nodes in the setting of primary tumors." (PMID 19835631, 2009). "MMP1-expressing CAFs were frequently positioned at the stromal interface, suggesting a role in facilitating cell movement across the tumor boundary." (PMID 42079046, 2026). "Matrix metalloproteinases (MMPs), and in particular MMP-1, play a pivotal role in tumor progression by degrading extracellular matrix components through a Zn(II)-dependent catalytic mechanism." (PMID 41539668, 2026). "A comprehensive pan-cancer analysis revealed that MMP-1 is significantly upregulated in various cancers, indicating its potential involvement in tumor progression." (PMID 40724896, 2025). "strain) significantly inhibits metastasis of tumor cells by regulating the Notch signaling pathway and the expression of EMT-associated factors β-integrin and MMP1 in Drosophila, as well as growth, migration, and invasion of MDA-MB-231 cells." (PMID 40151788, 2025). "Analysis of the immune cycle indicated that MMP1 impairs T-cell function across four common tumor types." (PMID 40394037, 2025). "The presence of MMP1+ malignant cells in the TME suggested that MMP1 not only facilitated tumor cell invasion and metastasis, but also played a critical role in immune evasion by modulating the function of immune cells, including macrophages and CD8+ T cells." (PMID 40394037, 2025). "In tumor, MMP1’s ability to degrade ECM components facilitates tumor cell invasion and metastasis by breaking down physical barriers within the ECM." (PMID 40394037, 2025). "MMP-1 is frequently upregulated in cancer and contributes to tumor invasion and metastasis by breaking down the ECM barriers that normally confine cells." (PMID 39869563, 2025). "This concept of exosome-mediated mRNA delivery is supported by recent reports of extracellular vesicles carrying MMP1 mRNA 37, and tumor exosomal RNAs promoting dissemination." (PMID 40756343, 2025). "Current research indicates that tumor-associated macrophages (TAMs) secrete various inflammatory cytokines, such as IL-1β, which facilitate the invasion of RCC by activating MMP-1 and other matrix metalloproteinases." (PMID 39976778, 2025). "A study using a xenograft model of breast carcinoma cells initially demonstrated a critical role for MMP‐1 derived from tumor‐infiltrating fibroblasts in the cleavage of PAR1, which appears to drive the migration and invasive behavior of cancer cells." (PMID 40969301, 2025). "Through these analyses, we elucidated how MMP1 contributes to the malignant behavior of tumor cells and their interactions with immune cells." (PMID 40394037, 2025). "Our analysis of clinical data in the TCGA database shows that higher MMP1 and RUNX2 levels in tumor tissues are associated with higher tumor grade and stage and poorer overall outcomes of RCC patients." (PMID 40386045, 2025). "There is cumulative evidence that the Toll pathway promotes tumor progression through activation of JNK signaling, a pathway well established to trigger tumor cell invasion through activation of matrix metalloproteinase gene mmp1." (PMID 40143968, 2025). "Research indicates that MMP1 contributes to resistance by influencing cell signaling, modifying the tumor microenvironment, and altering ECM composition." (PMID 40287412, 2025). "In this study, we utilized large-scale single-cell RNA sequencing and spatial transcriptomics to investigate MMP1 expression, its cellular localization, and its impact on tumor progression and immune modulation." (PMID 40394037, 2025). "The downregulation of MMP1, in conjunction with SG treatment, significantly inhibited tumor growth and migration compared to SG treatment alone, indicating the potential to reverse SG resistance." (PMID 40287412, 2025).
tumor (continued). "Based on the close relationship between Notch signal and EMT and their central roles in tumor cell migration and metastasis, the expressions of β-integrin and MMP1 were measured using immunohistochemistry staining to identify potential mechanisms." (PMID 40151788, 2025). "At ST resolution, MMP1 expression demonstrated a similar localization pattern with malignancy, showing a strong positive correlation with tumor cells." (PMID 40394037, 2025). "By targeting MMP1, we aim to suppress tumor progression and enhance the efficacy of existing therapeutic strategies." (PMID 40394037, 2025). "As a member of the MMP family, MMP1 directly facilitates tumor cell invasion and distant metastasis by degrading ECM and basement membrane components." (PMID 40809844, 2025). "Our findings reveal that MMP1 expression is elevated in various tumor types and is strongly correlated with metastatic potential." (PMID 40394037, 2025). "In EOC cells, MMP1 can be secreted into the tumor microenvironment via vesicles, enhancing the invasive capacity of the tumor cells." (PMID 40535817, 2025). "Across pan-cancer analyses, MMP1 expression showed the strongest positive correlation with tumor cell metastasis scores and was significantly upregulated in the majority of tumors." (PMID 40394037, 2025). "Exploring the interplay between MMP1 and other signaling pathways, as well as the influence of the tumor microenvironment, will be crucial for developing comprehensive therapeutic strategies." (PMID 40287412, 2025). "DTX influences the tumor microenvironment and upregulates the MMP1 gene, increasing collagenolytic MMPs." (PMID 40245075, 2025). "These advanced technologies provided a detailed understanding of MMP1 expression patterns and their spatial distribution within the tumor microenvironment." (PMID 40394037, 2025). "To further investigate, we conducted a series of MMP1 knockdown assays in tumor cell lines (MCF-7 and SW480)." (PMID 40394037, 2025). "Prior research has predominantly focused on the role of MMP1 in tumor invasion and metastasis through ECM degradation, with its involvement in chemoresistance being less explored." (PMID 40287412, 2025). "Essentially, MMP-1 functions as an interstitial collagenase that is active in extracellular matrix and vascular remodeling, angiogenesis, and tumor progression." (PMID 40843692, 2025). "The activation of neutrophils and the secretion of MMP1 played a significant role in tumor-immune evasion and tumor progression." (PMID 40394037, 2025). "In BC, MMP1 is frequently overexpressed and is significantly correlated with enhanced tumor invasiveness and metastatic potential." (PMID 41425594, 2025). "IL-8, for example, has been shown to activate fibroblasts via STAT3 phosphorylation, upregulating MMP1 and promoting tumor cell invasion." (PMID 40472740, 2025). "In vivo experiments also showed that MMP1 knockdown inhibited tumor growth in mice compared to the control group, leading to reductions in tumor volume and weight." (PMID 41425594, 2025). "While much of the existing research has centered on MMP1’s role in facilitating tumor cell invasion through the stroma and blood vessel walls to drive metastasis, its critical involvement in tumor immunology warrants greater attention." (PMID 40394037, 2025). "Through ECM remodeling, MMP1 alters the accessibility and functionality of immune cells, potentially affecting their ability to mount effective anti-tumor responses." (PMID 40394037, 2025). "Matrix metalloproteinase 1 (MMP1) plays a pivotal role in tumor biology and immune regulation due to its critical function in extracellular matrix (ECM) remodeling." (PMID 40394037, 2025). "Matrix metalloproteinase 1 (MMP1), which is overexpressed in many tumor types, plays a key role in tumor metastasis and drug resistance." (PMID 40287412, 2025).
tumor (continued). "Our findings position MMP1 as a key player in the “tumor-immune” vicious cycle and a promising therapeutic target to enhance anti-tumor responses and improve patient outcomes." (PMID 40394037, 2025). "The role of MMP1 in modulating the tumor microenvironment (TME) has been well documented, and RNF2, which functions as an E3 ubiquitin ligase, plays a crucial role in regulating cell-cycle progression and the DNA damage response." (PMID 40809844, 2025). "Previous studies have suggested that elevated levels of MMP-1 correlate with increased tumor aggressiveness and poor prognosis in various types of carcinomas." (PMID 40564842, 2025). "Through large-scale ST and scRNA-seq analyses, we identified that elevated MMP1 expression in malignant cells not only enhances their EMT capabilities but also facilitates significant interactions between tumor cells and immune cells." (PMID 40394037, 2025). "Specifically, high MMP1 levels in BC have been shown to reduce the sensitivity of tumor cells to chemotherapeutic agents, whereas MMP1 inhibition significantly restores drug responsiveness in resistant cancer cells." (PMID 41425594, 2025). "It was noteworthy that we also observed a close correlation between MMP1 expression and neutrophil infiltration in the tumor microenvironment in certain cancer types." (PMID 40394037, 2025). "Compared to the control (A’, D’), protein expression levels of β-integrin and MMP1 were upregulated in the eyeful tumor model, though the upregulation was inhibited after treatment with 25.00 mg/mL Binpu-3RE (B’, C’, E’, F’)." (PMID 40151788, 2025). "Both clear cell and papillary RCCs exhibit much higher expression of MMP1 mRNA than non-tumor tissues." (PMID 40386045, 2025). "In summary, these findings suggest that MMP1 plays a crucial role in BCBM by promoting tumor cell migration, invasion, and VM formation." (PMID 40885703, 2025). "Tumor status analysis using the CancerSEA database revealed that MMP1 played a critical role in mediating various malignant phenotypes in BRCA and COAD, including cell apoptosis, proliferation, stemness, and invasion." (PMID 40394037, 2025). "This transformation was accompanied by a significant enhancement in tumor invasive ability, as evidenced by the abundant cell autonomous Mmp1 upregulation observed at the leading edge of the invasive tumor cells (C’)." (PMID 39516282, 2024). "MMP1, a matrix metalloproteinase, plays a critical role in extracellular matrix remodeling and is involved in tumor invasion, metastasis, and angiogenesis." (PMID 38409471, 2024). "Dysregulation of MMP1 transcription promotes tumor metastasis because of its role in extracellular matrix degradation in tumor invasion." (PMID 38410799, 2024). "Staining revealed MCAF localization in large patches encasing tumor cells and at the tumor-stroma border, while iCAFs were intermixed with MMP1-, COL1A1 cells clustered within tumors." (PMID 38525245, 2024). "Among these, Mmp1 was found to activate TGF-β via Gbb in both the tumour and the fat body, leading to organ wasting." (PMID 39682725, 2024). "IHC staining images have shown that the overexpression of MMP1 in tumor tissue compared to normal tissue." (PMID 38356704, 2024). "Our findings reveal a novel mechanistic pathway where AGBL4 enhances GBM malignancy primarily through modulation of MMP-1 expression, which in turn influences the inflammatory response pathways within the tumor microenvironment." (PMID 39007144, 2024). "To investigate the effects of SPHK1 and MMP1 expression on tumor biology, we initially generated SCC7 cells from HNSCC mice with normal immune function and stably overexpressed or knocked down SPHK1 or MMP1." (PMID 39629135, 2024). "The oncogenic protein tyrosine kinase (KIT)-containing exosomes trigger the conversion of progenitor smooth muscle cells to tumour-like phenotype and mediate the release of MMP-1." (PMID 38200509, 2024).